AIM2 (absent in melanoma 2)
Diseases named in the same sentence as AIM2 in open-access papers (continued):
Sharing a sentence is not in itself a finding about the gene and the disease.
COVID-19 (continued). "Neutrophils from patients with COVID-19 exhibited ASC spot fluorescence, with the highest intensity in colocalization with NLRC4 protein (48% patients), followed by NLRP3 (28.9%), AIM-2 (15%), and NLRP1 (13.9%)." (PMID 37047314, 2023). "In this study, we investigated the ZBP1, AIM2, and MDA5 expression levels in COVID-19 patients with different intensities of the disease." (PMID 36320810, 2022). "The expression levels of ZBP1 (P=0.001), AIM2 (P=0.001), and MDA5 (P= 0.003) transcript were significantly higher in COVID-19 patients than the control group." (PMID 36320810, 2022). "Similar to the mDC subsets, the NLRP1, AIM2, NAIP expression was also highly activated pDCs from the in COVID-19 groups." (PMID 36439166, 2022). "The results also revealed that the expression levels of ZBP1, AIM2, and MDA5 were significantly higher in the critical and severe COVID-19 patients compared to those with mild disease (P<0.05)." (PMID 36320810, 2022). "Regarding the subjects' gender, data analysis showed that the expression level of AIM2 and MDA5 mRNA was significantly increased in the male critical and severe COVID-19 patients than females in the same stage." (PMID 36320810, 2022). "Indeed, infected SARS-CoV-2 monocytes have been shown to undergo AIM2 and NLPR3-inflammasome-mediated pyroptosis and cytokine release, contributing to COVID-19 immunopathology." (PMID 40788382, 2025). "During severe COVID-19, mitochondrial (mt) DNA and/or cell free DNA play an important role in triggering inflammatory responses and following cytokine storms, which can increase ISG mRNA such as AIM2." (PMID 36320810, 2022). "Importantly, stimulation of AIM2 responses in PBMCs obtained from both non-fibrotic or fibrotic PC patients, did not induce increases of IL-1β, a cytokine which is elevated in COVID-19 and correlates with disease symptoms." (PMID 35844548, 2022). "Our observation that two of the targeted methylated genes within EPIMISC were shared with severe adult COVID-19 cases (AIM2 and PM20D1) prompted us to investigate whether the EPIMISC signature was also present in non-pediatric COVID-19 cases." (PMID 35770252, 2022).
ischemic stroke (22 papers, 2020 to 2026). A stroke disorder caused by obstruction of blood flow to the brain, due to thrombotic (local blood clot formation) or embolic (due to a blood clot or other material traveling from another site) event. "In subsequent experiments, we investigated the mechanisms underlying the beneficial effects of AIM2 on the BBB after ischemic stroke." (PMID 34156153, 2021). "In ischemic stroke, multiple inflammasomes (NLRC4, NLRP1, NLRP3, NLRP6, AIM2) have been implicated, with AIM2 uniquely recognizing cytosolic dsDNA to drive AIM2-ASC-caspase-1 complex formation and GSDMD-mediated pyroptosis." (PMID 41344159, 2025). "The AIM2 inflammasome is an essential mediator of neuroinflammation and provides a valuable therapeutic target for ischemic stroke." (PMID 40351418, 2025). "A151 inhibits neuroinflammatory responses by inhibiting the production of inflammasome AIM2, consequently reducing neuronal cell death in ischemic stroke." (PMID 37915571, 2023). "Emerging evidence also supports the critical role of AIM2 inflammasome in ischemic brain damage, for instance, ischemic stroke." (PMID 37817895, 2023). "AIM2 was shown to be expressed in brain endothelial cells and upregulated after ischemic stroke in the mouse brain." (PMID 34156153, 2021). "This multimeric protein complex is also called the AIM2 inflammasome and has been demonstrated to be a critical mediator of the neuroinflammatory response during ischemic stroke." (PMID 34156153, 2021). "Previous work indicates that deletion or inhibition of the AIM2 inflammasome alleviates brain injury after ischemic stroke." (PMID 34740380, 2021). "Recent studies suggested that inhibition of NF-κB/AIM2 signaling pathway contributed to attenuating neuroinflammation and improving neurological function in intracerebral hemorrhage and ischemic stroke." (PMID 40351418, 2025). "Activation of the AIM2 inflammasome aggravated ischemic stroke." (PMID 39600708, 2024). "Although the precise mechanism by which the cGAS-STING pathway and AIM2 participate in the inflammatory reaction during ischemic stroke remains ambiguous, the interaction of downstream NF‐κB with GSDMD or type I IFN with AIM2 may be involved." (PMID 37915571, 2023). "Furthermore, PBM treatment with 630‐nm LEDs attenuated AIM2 inflammasome activation and inflammasome‐mediated pyroptosis and modulated microglial polarization in the hippocampus and cortex 7 days following ischemic stroke." (PMID 35076161, 2022). "Additionally, our previous study revealed that a selective inhibitor of histone deacetylase 3 (HDAC3) alleviated the inflammatory response and protected against ischemic stroke by suppressing the activation of the AIM2 inflammasome in microglia." (PMID 34156153, 2021). "Firstly, the effects of AIM2 in ischemic stroke were studied in global gene knockout mice." (PMID 34156153, 2021). "AIM2 inflammasomes are a common focus of ischemic stroke research." (PMID 34740380, 2021). "To verify whether the AIM2 expression level changed after ischemic stroke, we first analyzed AIM2 expression in the brains of mice after MCAO by Western blot." (PMID 34156153, 2021). "This study aimed to explore the effects of AIM2 on BBB integrity after ischemic stroke." (PMID 34156153, 2021). "Based on the results of the in vivo and in vitro experiments, we next investigated whether AIM2 deletion benefits BBB integrity after ischemic stroke." (PMID 34156153, 2021). "Mechanistic studies indicated that AIM2 inflammasome could contribute to brain damage and neuroinflammation after ischemic stroke." (PMID 32239625, 2020). "Nonetheless, this study was limited to examining the role of AIM2 in ischemic stroke using whole-gene knockout mice and did not clarify whether the AIM2 inflammasome was implicated." (PMID 39600708, 2024). "Therefore, AIM2 must play a central role in brain endothelial cells after ischemic stroke." (PMID 34156153, 2021).
ischemic stroke (continued). "Scientists generated AIM2 knockout mice and administrated RGFP966 intraperitoneally at 10 mg/kg after ischemic stroke injury." (PMID 37817895, 2023). "Despite these findings, a detailed characterization of the role of AIM2 in BBB damage, especially in endothelial cells, after ischemic stroke remains elusive." (PMID 34156153, 2021). "The deletion of AIM2 (absent in melanoma 2) and NLRC4 (NLR family CARD domain-containing protein 4) as two candidates proved to be protective after ischemic stroke." (PMID 32645874, 2020). "The GMDR analysis revealed that the combination of MPO-DNA, AIM2, and IL-1β exert a synergistic effect on the prognosis of LAA stroke, which indicated NETs/AIM2/IL-1β axis may involve in inflammatory damage after ischemic stroke." (PMID 39737165, 2024). "Our findings indicated that inhibiting AIM2 preserved the BBB integrity after ischemic stroke, at least partially by modulating STAT3 activation and that AIM2 may be a promising therapeutic target for cerebral ischemic stroke." (PMID 34156153, 2021). "We previously showed that the microglial inhibition of the inflammasome sensor absent in melanoma 2 (AIM2) suppressed the inflammatory response and protected against ischemic stroke." (PMID 34156153, 2021). "Similarly, inhibiting AIM2 inflammasome activation or double-stranded DNA (a trigger of the AIM2 inflammasome) alleviates GSDMD-induced pyroptosis and ameliorates brain injury after ischemic stroke." (PMID 34740380, 2021). "Considering that both caspase‐1 and IL‐1β are key components of the AIM2 inflammasome, we hypothesized that AIM2 plays a crucial role in mediating BBB integrity after ischemic stroke." (PMID 34156153, 2021). "Recent studies showed that various inflammasomes, containing NLRP1, NLRP2, NLRP3, NLRP10, NLR family card domain containing 4 (NLRC4), and absent in melanoma 2(AIM2) 35-39, are activated in ischemic stroke." (PMID 32788872, 2020). "However, as with E2, little is known about its impact on inflammasomes and especially on the AIM2 and NLRC4 inflammasomes after ischemic stroke." (PMID 32645874, 2020). "17β-estradiol plus P displayed anti-inflammatory effects by selectively reducing absent in melanoma 2 (AIM2) and NLR family CARD domain-containing protein 4 (NLRC4) inflammasomes in primary cortical astrocytes and microglia after ischemic stroke in rats." (PMID 36569944, 2022). "However, the role of AIM2 and NLRC4 inflammasomes and the influence of the neuroprotective steroids 17β-estradiol (E2) and progesterone (P) on their regulation after ischemic stroke have not yet been conclusively elucidated." (PMID 32645874, 2020).
Cerebral ischemia (19 papers, 2020 to 2025). Restriction of arterial blood supply to the brain associated with insufficient oxygenation to support the metabolic requirements of the tissue. "Briefly, our findings provide a novel strategy for tuning the balance between AIM2-associated inflammation and autophagy activation to maintain neuroprotection during cerebral ischemia." (PMID 34740380, 2021). "Indeed, NLRC4 and AIM2 inflammasomes have been implicated in brain ischemia, as a study showed that after transient ischemic stroke, mice with global deletion of Nlrc4 or Aim2 have smaller infarct volumes and better neurologic scores compared to wild-type mice." (PMID 32867797, 2020). "We found that the expression of AIM2, pro‐caspase‐1, p20 caspase‐1, and ASC increased after cerebral ischemia, suggesting the activation of the AIM2 inflammasome, and this increase was reversed upon 3‐HKA treatment." (PMID 39854137, 2025). "Univariate analysis and multivariate analysis were sequentially done to ascertain relationship between serum AIM2 levels, severity, delayed cerebral ischemia (DCI) and 90-day poor prognosis (mRS scores of 3–6)." (PMID 38714826, 2024). "Long noncoding RNA MEG3 promotes cerebral ischemia‒reperfusion injury by targeting the miR-485/AIM2 axis to increase pyroptosis." (PMID 38102696, 2023). "Expression of AIM2 in neural cells, microglia, neurons, but also endothelium was increased in response to brain ischemia." (PMID 37212886, 2023). "(ii) Which role do NLRC4 and AIM2 play upon functional inhibition of microglial NLRP3 after cerebral ischemia?" (PMID 34628598, 2022). "Down-regulation of MEG3 can reduce cerebral ischemia-reperfusion pyroptosis and neuroinflammation through the miR-485/AIM2 signaling pathway, down-regulate the expression of AIM2 in the inflammasome." (PMID 36275741, 2022). "Accumulating evidence has demonstrated that the AIM2 inflammasome plays a crucial role in cerebral ischemia." (PMID 34740380, 2021). "In summary, our present study suggests that AIM2/STAT3 inhibition in endothelial cells is a promising therapeutic strategy for BBB impairment after cerebral ischemia." (PMID 34156153, 2021). "For instance, during ischemic stroke, brain ischemia leads to the release of double-stranded DNA (dsDNA) into the cytoplasm, activating the cyclic GMP-AMP synthase (cGAS) signaling pathway and the AIM2 inflammasome in microglia." (PMID 39994107, 2025). "AIM2, together with NLRC4, contribute to inflammation and subsequent inflammatory injury after brain ischemia." (PMID 37212886, 2023). "To further assess the influence of cerebral ischemia on the activation of TAK1 and the inflammasomes NLRP3, NLRC4, and AIM2, we first compared the protein expression of TAK1 and its phosphorylation (pTAK1) in mice after tMCAo or sham surgery." (PMID 34628598, 2022). "In conclusion, in its acute phase, cerebral ischemia not only leads to increased expression but also to enhanced activation of TAK1 and the inflammasome complexes of NLRP3, NLRC4, and AIM2." (PMID 34628598, 2022). "However, whether AIM2 is involved in BBB disruption during cerebral ischemia is unknown." (PMID 34156153, 2021). "Next, we performed co‐localization analysis of AIM2 with NeuN (a neuronal marker), GFAP (an astrocyte marker), Iba1 (a microglial marker), and CD31 (an endothelial cell marker) in the penumbral area at days 7 and 14 after cerebral ischemia." (PMID 39854137, 2025). "By targeting miR-485/AIM2 axis, MEG3 promotes cerebral ischemia/reperfusion injury." (PMID 35256601, 2022). "Moreover, Liang and colleagues have indicated AIM2 as a direct target of miR-485 and postulated that the long non-coding RNA MEG3 promotes cerebral ischemia-reperfusion injury by increasing pyroptosis by targeting the miR-485/AIM2 axis." (PMID 32645874, 2020).
Cerebral ischemia (continued). "In cerebral ischemia and neurodegenerative diseases, cytosolic double-stranded DNA (dsDNA) activates the cyclic GMP-AMP synthase (cGAS) signaling pathway in microglia, promoting the expression of (Absent in melanoma 2) AIM-2/ NLRP3 and GSDMD, which leads to cell polarization and pyroptosis." (PMID 39994107, 2025).
periodontitis (19 papers, 2016 to 2025). An acute or chronic inflammatory process that affects the tissues that surround and support the teeth. "This study demonstrates that bacterial and metallic components drive the activation of both NLRP3 and AIM2 inflammasomes in macrophages, highlighting their roles in the inflammatory responses associated with periodontitis and peri-implantitis." (PMID 40490723, 2025). "The present findings found significant association (p<0.05) of age, sex, BMI, socioeconomic status, tooth brushing frequency, clinical periodontal parameters, and AIM2 gene polymorphism with susceptibility to periodontitis and CHD." (PMID 41194911, 2024). "The presence of the T allele and (GT, TT) genotypes of the AIM2 gene, which reveal a wide range of effects on several traits, corresponds to increased vulnerability to both periodontitis and CHD." (PMID 41194911, 2024). "Association of AIM2 gene polymorphism with susceptibility to periodontitis and coronary heart disease and severity using multiple logistic regression model." (PMID 41194911, 2024). "An analysis of the AIM2 gene’s single nucleotide polymorphism linked the AIM2 gene’s downstream functional area to the occurrence of periodontitis and coronary heart disease through abnormal gene expression and activation of AIM2 proteins and host molecules." (PMID 41194911, 2024). "Integrative analysis of GWAS and expression quantitative trait loci data further identified AIM2 as a susceptibility gene for periodontitis." (PMID 32903550, 2020). "Furthermore, activation of the AIM2 inflammasome in THP-1 macrophages by porphyromonas gingivalis infection had been implicated in the pathogenesis of periodontitis." (PMID 39600708, 2024). "Notably, this study has found pleiotropy role of AIM2 SNP between periodontitis and CHD; the same genetic variant has been observed as being associated with both CHD diseases and periodontitis." (PMID 41194911, 2024). "A genome-wide association study confirmed AIM2 to be a risk gene for periodontitis development." (PMID 35003389, 2021). "In a more recent study, a decrease in AIM2 for chronic periodontitis patients was reported, with an increasing trend in the expression of caspase-1 between chronic periodontitis, aggressive periodontitis groups, and healthy subjects." (PMID 41440367, 2025). "Patients with polymorphisms in the AIM2 and PYCARD genes reported a susceptibility to periodontitis." (PMID 41440367, 2025). "NLRP3 expression is elevated in the serum and saliva of periodontitis patients, and AIM2 expression has been confirmed in the gingival tissues of both periodontitis and gingivitis patients." (PMID 38921772, 2024). "The data contains the details of age, sex, body mass index (BMI), Aim2 genotypes, clinical parameters for periodontitis and coronary heart disease patients with genetic variation of AIM2 gene." (PMID 41194911, 2024). "This can lead to the production of abnormal AIM2 polypeptides and increase the release of inflammatory mediators in both periodontitis and atheroma formation." (PMID 41194911, 2024). "Along with increased IL-1β processing, the activation of inflammasomes, such as NLRP3 and AIM2, is frequently detected in chronic periodontitis and aggressive periodontitis." (PMID 34177950, 2021). "Further analysis by our group showed that multiple genes encoding inflammasome components, including Aim2, Ifi204 (the mouse homolog of IFI16), and Nlrp3, exhibit increased expression in gingival tissues of murine experimental periodontitis." (PMID 32533779, 2020). "Recent research has found early evidence for the AIM2 inflammasome in a variety of periodontitis diagnoses." (PMID 32903550, 2020). "Later, the expression of AIM2 has been confirmed in broader types of periodontitis gingival tissues, including chronic periodontitis, aggressive periodontitis, and gingivitis." (PMID 32903550, 2020). "The expression of AIM2 in the gingival tissues of chronic periodontitis patients has been confirmed." (PMID 32903550, 2020).